INS (insulin)
Diseases named in the same sentence as INS in open-access papers (continued):
Sharing a sentence is not in itself a finding about the gene and the disease.
Hyperglycemia (continued). "ob/ob mice exhibit early‐onset obesity with hyperphagia, low energy expenditure, and insulin resistance but only mild hyperglycemia." (PMID 41030912, 2025). "The SmartGuard® automatic mode works for daily insulin dosages above 8 U/day and is able to adapt basal insulin delivery and to deliver a correction bolus in case of hyperglycaemia every 5 minutes." (PMID 40642512, 2025). "While exogenous insulin is fundamental in managing hyperglycemia in patients with active T1D, its potential to halt or slow the disease progression is still not clear." (PMID 40076938, 2025). "These animals received insulin treatment to prevent ketosis and severe hyperglycemia, as indicated by the red line in the graphs." (PMID 41329353, 2025). "DM is featured in hyperglycemia, resulting from dysfunction in insulin synthesis and secretion by pancreatic β-cells and/or impaired insulin sensitivity." (PMID 41189666, 2025). "Excessive, repeated, and inappropriate use of insulin to correct mild hyperglycemia outside of meals during pregnancy can lead to severe iatrogenic hypoglycemia." (PMID 40671052, 2025). "This process is saturable and can be regulated by insulin itself and other pathophysiological factors such as triglycerides and hyperglycaemia, as well as other serum factors." (PMID 39165238, 2025). "These additional cells produce adipokines to regulate carbohydrate metabolism and its sensitivity to insulin that finally favors inflammation and hyperglycemia processes." (PMID 41137228, 2025). "In relevant animal models, the increased insulin release after activating FXR cannot fully correct severe hyperglycemia." (PMID 40650120, 2025). "Rebound hyperglycemia was defined as glucose greater than 180 mg/dL within the first six hours after discontinuation of insulin infusion." (PMID 40978981, 2025). "Chronic exposure to hyperglycaemia, lipotoxicity, and glucotoxicity impairs β-cell function and viability, leading to progressive deterioration of insulin secretion capacity." (PMID 39982365, 2025). "Indigo supplementation increased Lactobacillus abundance in the gut, stimulated IL-22 production, protected pancreatic β-cells from inflammation, reversed hyperglycemia-induced damage, and improved insulin sensitivity." (PMID 41440753, 2025). "FOXO1 normally remains inactive in pancreatic β-cells under normal conditions but is activated in response to hyperglycemia, and loss of FOXO1 function in β-cells has been found to correlate with reduced insulin secretion." (PMID 40951426, 2025). "As ad libitum and fasting hyperglycemia precedes decreased serum insulin in SCD mice, these data suggest the possibility of progressive pancreatic β cell dysfunction in the presence of 2 copies of HbS." (PMID 40294908, 2025). "Compensatory hyperinsulinemia initially mitigates hyperglycemia but ultimately drives β-cell exhaustion through endoplasmic reticulum stress and apoptotic pathways, culminating in irreversible insulin secretion defects." (PMID 40429918, 2025). "As a result, hepatocytes become less responsive to insulin, leading to increased hepatic gluconeogenesis and systemic hyperglycemia." (PMID 40453076, 2025). "Laboratory investigations revealed hyperglycemia, ketoacidosis, and depleted insulin levels, leading to a diagnosis of F1DM." (PMID 40135013, 2025). "HSP90 inhibitors reversed hyperglycaemia in diabetic db/db mice and improved insulin sensitivity in insulin-resistant obese mice, further supporting the concept that the HSF1 pathway is a potentially viable anti-diabetic target." (PMID 41488136, 2025). "It is characterized by hyperinsulinemia, the presence of positive insulin antibodies, hyperglycemia, hypoglycemia, or alternative episodes of both following exogenous insulin administration." (PMID 41234224, 2025). "At 10 weeks posttransplantation, despite persistent hyperglycemia in both groups, grafts contained substantial numbers of insulin+ cells." (PMID 41140368, 2025).
Hyperglycemia (continued). "On the other hand, the response induced by insulin to hyperglycemia generates an abnormal metabolic process in lipids, leading to small, dense, and oxidized low-density cholesterol." (PMID 40429692, 2025). "Similar to neonatal presentation, intravenous administration of high calorie (additional intake of 100–120 kcal/kg/day), high carbohydrate fluids (10% dextrose) and lipids to prevent catabolism as well as insulin to correct hypoglycaemia and hyperglycaemia." (PMID 41250200, 2025). "These strategies include cognitive techniques, pre-competition aerobic exercises, and administering temporary basal rate increases or partial bolus insulin to correct hyperglycemia." (PMID 39823464, 2025). "By preserving endogenous incretins, Ericaceae phenolics help sustain insulinotropic signaling, improve meal-time insulin release, and attenuate postprandial hyperglycemia." (PMID 40430501, 2025). "Sustained hyperglycemia and impaired insulin signaling in T2DM patients potentiate amyloidogenic processing while compromising tau protein homeostasis, thereby accelerating the neuropathological cascade characteristic of AD progression." (PMID 40831951, 2025). "CGM revealed a high incidence of early postoperative hyperglycemia despite conventional sliding-scale insulin therapy." (PMID 41157267, 2025). "The impairment of insulin action and mitochondrial ATP production was attributed to hyperglycemia/glucotoxicity, iatrogenic hyperinsulinemia, or previous inadequate metabolic control justified by the long duration of T1D (metabolic memory effect)." (PMID 39998445, 2025). "Preclinical studies have demonstrated that MSCs can ameliorate hyperglycemia, improve insulin sensitivity, and alleviate DM complications, including neuropathy and nephropathy." (PMID 40244194, 2025). "Feeding an HFD to mice with Stat3+/+ myeloid cells led to hyperglycemia, hyperinsulinemia, and an intolerance to both glucose and insulin." (PMID 40801626, 2025). "The liver, a collection of insulin-sensitive tissues, is one of the vital organs vulnerable to oxidative stress engendered by hyperglycemia." (PMID 39846548, 2025). "One study initiated insulin in patients with persistent hyperglycemia beyond the early postoperative period." (PMID 40995094, 2025). "The present study highlights the adverse effects of maternal hyperglycemia during the pregnancy period and the role of treatment by insulin on neonatal hippocampal development, focusing on autophagy regulation and hippocampal morphology." (PMID 40660790, 2025). "Hyperglycemia induces oxidative stress and inflammation, which are detrimental to β-cell function and insulin sensitivity, and subsequently leads to diabetes." (PMID 40791231, 2025). "Hyperglycemia remains a significant challenge in the clinical application of PI3K inhibitors due to the PI3K/Akt pathway’s role in insulin-mediated glucose uptake." (PMID 40386392, 2025). "Insulin therapy is always and strictly necessary in older people with T1D to avoid hyperglycaemia and diabetic ketoacidosis." (PMID 39500566, 2025). "Exogenous insulin administration is a potent treatment for severe hyperglycemia or when adequate management of the glycemic status cannot be achieved despite using different oral hypoglycemic drugs." (PMID 40700168, 2025). "An example of actively engaging in insulin restriction to induce hyperglycemia would be intentionally reducing a dose of insulin relative to the carbohydrate content of a meal or snack." (PMID 40958557, 2025). "Insulin initiation should always be considered if symptoms of hyperglycemia are present and when HbA1c levels exceed 10% or blood glucose levels are >300mg/dL." (PMID 40507585, 2025). "Hyperglycaemia will further increase insulin secretion rates, with knock‐on effects on hepatic lipogenesis, spinning the liver cycle faster and hence the same for the pancreas cycle." (PMID 39898429, 2025).
Hyperglycemia (continued). "Acute management includes intravenous administration of high calorie and high carbohydrate fluids (additional intake of 100–120 kcal/kg/day; 10% dextrose) and lipids to prevent catabolism as well as insulin to correct hypoglycaemia and hyperglycaemia." (PMID 41250200, 2025). "Decreased phosphorylation of FOXO1 affects its protein levels and transcriptional activity, activating genes related to gluconeogenesis, thereby increasing glucose production and exacerbating hyperglycemia in insulin-resistant cells." (PMID 40951426, 2025). "The issue cascades under hyperglycemia or increased blood glucose, which is carried on through either the physique’s struggle with insulin or inadequate production of insulin." (PMID 40277568, 2025). "There is an ongoing discussion about the use of high-dose MP after pancreas or islet transplantation to rescue beta-cell function in case islet rejection is suspected on the basis of (progressive) hyperglycemia and the need for insulin therapy." (PMID 40371054, 2025). "Persistent hyperglycemia places additional stress on pancreatic beta cells, impairing insulin secretion and worsening glucose intolerance." (PMID 40076739, 2025). "Achieving optimal insulin dosing that accurately matches metabolic needs is challenging, often resulting in fluctuating glucose levels and episodes of hyperglycemia or hypoglycemia." (PMID 40742490, 2025). "T2DM is characterized by defective insulin secretion by pancreatic β-cells and an impaired tissue response to insulin, leading to hyperglycemia." (PMID 41400625, 2025). "Key factors include insulin and insulin-like growth factor-1 (IGF-1) deficiency, chronic hyperglycaemia, accumulation of advanced glycation end products, increased marrow adiposity, and inflammation." (PMID 41334715, 2025). "β-cell dysfunction manifests as inadequate insulin secretion or decompensation, ultimately resulting in hyperglycemia." (PMID 40831951, 2025). "Cytokines, fatty acids, hyperglycemia, mitochondrial dysfunction, endoplasmic reticulum (ER) stress, and insulin induce inhibitory Ser/Thr phosphorylation of IR, notably IRS-1 and -2, via JNK, IKK, traditional and novel PKCs, mTORC1/S6K, and MAPK." (PMID 40141412, 2025). "Overfeeding can lead to adverse effects such as mitochondrial dysfunction, reduced autophagy, ketogenesis suppression, hyperglycemia, and excessive insulin utilization." (PMID 40416376, 2025). "The relationship between fasting hyperglycemia and elevated cortisol is largely attributed to glucocorticoid-induced hepatic gluconeogenesis and impaired insulin secretion, contributing to features of metabolic syndrome." (PMID 39980848, 2025). "IR can be characterized by hyperglycemia and hyperinsulinemia, indicating an inability of insulin to bind to insulin receptors which can be observed within the fasted state." (PMID 40052519, 2025). "Improved insulin sensitivity reduces the burden of hyperglycemia, indirectly contributing to the attenuation of oxidative stress linked to elevated glucose levels." (PMID 39136514, 2025). "The degree of catecholamine secretion was high enough to override residual insulin action, tipping the metabolic balance from isolated hyperglycemia to full ketoacidosis." (PMID 40584808, 2025). "Subcutaneous rapid-acting insulin analogs are recommended to correct hyperglycemia during the intra- and perioperative period." (PMID 40507441, 2025). "Since methylprednisolone is an intermediate‐acting glucocorticoid, the most suitable insulin for managing hyperglycemia is an intermediate‐acting basal insulin, such as NPH insulin." (PMID 40931439, 2025). "These hormones can stimulate the liver to produce more glucose and interfere with insulin action, contributing to hyperglycemia." (PMID 39847589, 2025). "Diabetics demonstrate an impaired suppression of adipose tissue lipolysis and an inability of insulin to inhibit hepatic glucose production, leading to chronic hyperglycaemia." (PMID 41179869, 2025).
Hyperglycemia (continued). "During GDM, AMPK activity is often reduced, impairing insulin signaling and increased glucose production, exacerbating hyperglycemia." (PMID 40136665, 2025). "Elevation of the maternal glucose level stimulates foetal hyperglycaemia, which in turn stimulates the release of foetal insulin." (PMID 39861104, 2025). "Hyperglycemia also augments insulin and insulin-like growth factor (IGF-1) signaling, activating the PI3K/AKT/mTOR pathway, which enhances cellular proliferation, survival, and angiogenesis while suppressing antitumor immune surveillance." (PMID 41479778, 2025). "The islet damage in T1DM mice was mitigated, and insulin secretion was enhanced, along with effective alleviation of hyperglycemia symptoms, due to the intervention of EUG." (PMID 39792010, 2025). "Results demonstrated that the combination significantly reduced hyperglycemia and improved insulin sensitivity more effectively than HUCMSCs alone." (PMID 41373625, 2025). "Despite intensive insulin therapy and adherence to dietary and exercise recommendations, his glycemic control remained poor, with persistent hyperglycemia." (PMID 41019343, 2025). "Zn supplementation has been shown to impair insulin signaling and glucose metabolism, leading to hyperglycemia and insulin resistance." (PMID 41459237, 2025). "The consequences of unsuccessful functions across ToC included incorrect doses of insulin being administered, which led to hypo‐or hyperglycaemia." (PMID 40696540, 2025). "A long-term HFD leads to excessive lipid influx into the liver and over-secretion of pro-inflammatory factors, thereby disrupting the insulin signaling pathway and enhancing hepatic gluconeogenesis, resulting in hyperglycemia." (PMID 39942052, 2025). "Hyperglycemia not only mediates cellular damage but also disrupts lipid synthesis and degradation, thereby exacerbating insulin resistance and perpetuating a vicious cycle of glucose and lipid metabolism." (PMID 40868893, 2025). "A well-known combination of factors - Pdx1, Ngn3, and MafA (PNM) has been shown to convert exocrine cells into insulin-producing β-like cells, ameliorating hyperglycemia in mice." (PMID 41584842, 2025). "β-cells, responsible for insulin synthesis and secretion, are destroyed under the influence of streptozotocin, leading to a significant decrease in insulin levels and, consequently, hyperglycemia." (PMID 40807271, 2025). "GLP-1 is an incretin hormone that is released by L-cells of the small intestines in response to nutrient intake and promotes insulin release to counteract the hyperglycaemia triggered by the meal." (PMID 40426955, 2025). "In this cycle, the excess fat in the liver hinders hepatic responsiveness to insulin, reducing glycogen synthesis and increasing gluconeogenesis, leading to hyperglycemia." (PMID 40426986, 2025). "Ferulic acid-rich rice bran extracts significantly reduced hyperglycemia and elevated plasma insulin in diabetic C57BL/KsJ-db/db mice." (PMID 40332518, 2025). "Studies have demonstrated that high sugar intake, particularly from rapidly digestible sugars such as lactose, can lead to postprandial hyperglycemia, which in turn stimulates insulin secretion and fat storage." (PMID 40357039, 2025). "It is particularly notable because the hyperglycaemia was transient, with the patient requiring insulin therapy for only 24 hours." (PMID 41556033, 2025). "Hyperglycemia is frequently observed in septic patients, often attributed to stress-induced hypermetabolism and insulin resistance." (PMID 40810063, 2025). "The inhibition of PDX-1 and EGFR signaling in the pancreas by chronic hyperglycemia results in impaired insulin synthesis and secretion and β-cell proliferation." (PMID 41189666, 2025). "There is a concomitant rise in circulating insulin to prevent maternal hyperglycemia and the rise in insulin demand is met by increased maternal β-cell mass." (PMID 40497429, 2025).
Hyperglycemia (continued). "Defects in insulin signaling under hyperglycemia decrease calcium sensitization and reduce sarcoplasmic calcium uptake in CMs, thus contributing to abnormal calcium flux during early DC pathogenesis." (PMID 39985023, 2025). "One or ten weeks after the onset of hyperglycemia, gut segments and the pancreas of control, diabetic, and insulin-treated diabetic rats were investigated." (PMID 40497986, 2025). "Over the past decades, hyperinsulinemia, hyperglycemia, overexpression of pro-inflammatory cytokines, and increased growth factor signaling have been proposed as cancer initiators in insulin-resistant cases." (PMID 41514592, 2025). "High insulin levels in response to hyperglycaemia stimulate keratinocyte proliferation and an increase in tissue and epidermal growth factors, resulting in the overgrowth of skin tags." (PMID 41179869, 2025). "Insulin therapy has proven effective in managing hyperglycemia, potentially slowing the inflammatory process by reducing the burden on the pancreas." (PMID 40937420, 2025). "Individuals experiencing rDKA often face challenges such as insulin delivery issues, ongoing hyperglycemia, substance use, and coexisting complications like diabetic neuropathy." (PMID 41149081, 2025). "This dysfunction results in an insufficient insulin supply, leading to hyperglycemia and subsequent disease onset." (PMID 40666490, 2025). "Specifically, offspring of HFD-fed dams exhibit hyperglycemia and altered insulin sensitivity, which can be attributed to epigenetic modifications affecting gluconeogenic pathways." (PMID 40218938, 2025). "Fulminant type 1 diabetes mellitus (F1DM) is a subtype of type 1 DM characterized by sudden onset with ketoacidosis, prominent hyperglycemia, and impairment of insulin secretion." (PMID 40135013, 2025). "Specifically, the PCE group exhibited a gradual decline in glucose tolerance and insulin sensitivity in the late stage (after PW36), accompanied by hyperglycemia and elevated blood insulin levels, indicative of the onset of IR." (PMID 40903796, 2025). "Fasting hyperglycemia appears due to elevated hepatic glucose production because of the relatively low insulin levels combined with hepatic insulin resistance." (PMID 40732311, 2025). "Treatment for DKA consists of aggressive fluid replacement and correction of the insulin deficit to help resolve the acidosis and hyperglycemia." (PMID 40978981, 2025). "These agents have demonstrated the ability to modulate carbohydrate metabolism by reducing fasting and post-meal hyperglycemia, enhancing tissue insulin sensitivity, and supporting pancreatic β-cell function." (PMID 41515170, 2025). "Conversely, at more positive cumulative differences, where average blood glucose is higher and average TIR is worse, the model suggests higher insulin doses to avoid hyperglycemia." (PMID 40425725, 2025). "In particular, global apoER2 deficiency reduces body weight and adiposity but accelerates hyperglycemia onset due to impaired glucose-induced insulin secretion." (PMID 40722764, 2025). "Insulin remains the most potent therapy for lowering glucose and is indispensable in advanced T2D, catabolic presentations, and severe hyperglycemia." (PMID 41010881, 2025). "Increased ROS levels impair antioxidant defenses, damage pancre-atic tissues, and inhibit insulin production, thereby aggravating hyperglycemia." (PMID 40584130, 2025). "In the present study, it was observed that dexamethasone at all doses triggered hyperglycaemia, an increase in glucose tolerance and a reduced insulin sensitivity." (PMID 41194975, 2025). "Sulfonylureas enhance insulin release from pancreatic beta cells, with their immediate onset of action proving beneficial in managing short-term glucocorticoid-induced hyperglycemia." (PMID 40426928, 2025). "Hyperglycemia recurred on day 7, necessitating insulin reinitiation with continuous glucose monitoring (CGM)." (PMID 40476119, 2025).